IL23A (interleukin 23 subunit alpha)
Diseases named in the same sentence as IL23A in open-access papers (continued):
Sharing a sentence is not in itself a finding about the gene and the disease.
skin papilloma (3 papers, 2013 to 2021). A benign papillary neoplastic growth on the skin composed of epithelial cells and a fibrous stalk. "Both IL-23A and IL-23R deficient mice were found to be resistant to chemical-induced skin papillomas or fibrosarcomas." (PMID 34093846, 2021).
Stroke (3 papers, 2014 to 2023). Sudden impairment of blood flow to a part of the brain due to occlusion or rupture of an artery to the brain. "There was a 3.3 fold non significant increase in IL-23R gene expression in γδT cells in the stroke patients (p>0.05) with a 1.1 fold non significant decrease in IL-23A gene expression (p>0.05)." (PMID 24840735, 2014).
Chronic colitis (2 papers, 2010 to 2024). A chronic inflammatory disease of the large intestine (colon, cecum and rectum). "The reduction of Il12a, Il12b, and Il23a expression was also observed in chronic colitis." (PMID 39113810, 2024). "In wt mice with chronic colitis, IL-23a, IL-13, NF-kB2, PTGS1, SMAD3 and SMAD7 (P≤0.05) were significantly down-regulated, with the largest variations affecting the expression of IL-23a and IL-13 (100- and 10-fold)." (PMID 20706593, 2010).
COVID-19 (2 papers, 2023 to 2024). A disease caused by infection with severe acute respiratory syndrome coronavirus 2. "Taken together, we found that COVID-19 severity in the Ghanaian cohort was associated with dysregulated inflammatory response mediated by MAL, IL1A, IL23A, CRNN, and S100A7 overexpression and suppression of antiviral immune response-related pathways." (PMID 38375062, 2024). "COVID-19 severity was associated with immune suppression, overexpression of proinflammatory cytokines, including CRNN, IL1A, S100A7, and IL23A, and activation of pathways involved in keratinocyte proliferation." (PMID 38375062, 2024). "IFNA1 also presented a robust positive correlation with CCL11, FASLG, and IL23A in severe patients, and their correlation power was gradually enhanced as COVID-19 severity increased." (PMID 36776879, 2023). "An elevated IFNA1 response displayed a strong negative correlation with IL12p40 and CX3CL1, whereas it presented a robust positive correlation with CCL11, FASLG, and IL23A, especially in severe COVID-19 patients." (PMID 36776879, 2023). "However, in this study, an upregulation of other pro-inflammatory cytokines, including CRNN, IL1A, IL23A, IVL, and S100A7, was associated with severe COVID-19." (PMID 38375062, 2024).
keratoconus (2 papers, 2022 to 2023). A degenerative, structural disorder of the eye, characterized by a cone-shaped protrusion of the cornea. "Notably, multiple interleukins (such as IL23A) and chemokines (such as CXCL1) significantly elevated in keratoconus DCs, indicating activated immune response in DCs during keratoconus pathogenesis." (PMID 35821117, 2022).
pemphigus (2 papers, 2019 to 2024). Pemphigus is a group of rare autoimmune diseases that cause blistering of the skin and mucous membranes (mouth, nose, throat, eyes, and genitals).This conditioncan occur at any age, but often strikes people in middle or older age. "In line with previous human pemphigus studies, the data presented here confirm the overexpression of IL-17A, IL-17F, IL-17RA, IL-23A, and IL-23R in canine PF skin." (PMID 38393106, 2024). "Further studies will be needed to evaluate whether inhibitors of the IL-17 pathway (e.g., IL-17A, IL-17A/IL-17F, and IL-23A) could be used to treat the pemphigus group of blistering diseases in humans and dogs." (PMID 38393106, 2024).
type 1 diabetes (2 papers, 2020 to 2025). "In vitro treatment with 1,25(OH)2D3 reduced proinflammatory cytokines (IL-6, CCL-2, IL-23A, IL-15) whereas anti-inflammatory cytokines (IL-10 and PD-L1) rose both in APS-type 1 diabetes and APS-Addison ́s disease." (PMID 33365026, 2020).
acute pancreatitis (1 paper, 2022). An acute inflammatory process that leads to necrosis of the pancreatic parenchyma. "RNA‐seq data discovered that compared to untreated mice, IL‐23a, IL‐17a, and IL‐17f were remarkably increased while cell cycle‐related molecules, including ATM, Cdk2, and Chk2, were decreased in the mice with acute pancreatitis." (PMID 35634959, 2022). "qPCR data also confirmed the upregulated levels of IL‐23a, IL‐17a, and IL‐17f and the downregulated levels of ATM, Cdk2, and Chk2 in the pancreatic tissues of mice with acute pancreatitis." (PMID 35634959, 2022).
anxiety disorder (1 paper, 2024). A category of psychiatric disorders which are characterized by anxious feelings or fear often accompanied by physical symptoms associated with anxiety. "Integrating the finding of IL-23A as a promising diagnostic biomarker into screening programs for groups at higher risk for anxiety disorders could be beneficial." (PMID 38956309, 2024).
aphthous ulcers (1 paper, 2025). "IL23 (subunits encoded by IL12B and IL23A), which is strongly implicated in IBD pathology, fell below the 5 TPM detection threshold, but both transcripts were increased > 5‐fold in aphthous ulcers versus Peyer's patches." (PMID 40386941, 2025).
depression (1 paper, 2024). "The IL-23A or IL-17A immunological axis, which is involved in autoimmune and inflammation-related diseases, might also have a function in the development of depression and anxiety disorders." (PMID 38956309, 2024).
endometriosis (1 paper, 2024). The growth of functional endometrial tissue in anatomic sites outside the uterine body. "Finally, IL-23a and its association with the IL-17 axis promotes endometriosis and is involved in the pathogenesis of this disease." (PMID 38999962, 2024).
eosinophilia (1 paper, 2023). "We found that the transcript levels of Il12a, Il12b, and Il23a were increased in the lungs of neutrophilia-dominant mice compared to the eosinophilia-dominant mice or the control mice." (PMID 37898756, 2023).
generalized anxiety disorder (1 paper, 2025). An anxiety disorder characterized by excessive and difficult-to-control worry about a number of life situations. "For example, IL-17A and IL-23A, two proinflammatory cytokines associated with Th17 activation, have shown promise as biomarkers for generalized anxiety disorder (GAD)." (PMID 40401059, 2025).
HIV-1 infection (1 paper, 2025). The type species of lentivirus and the etiologic agent of acquired immunodeficiency syndrome (AIDS). "Instead, expression of IRF5-regulated genes IL1A and IL23A was significantly downregulated in response to HIV-1 infection in MDMs from younger donors." (PMID 40493408, 2025). "These upregulated genes were primarily ISGs, including IRF5 and IRF7, as well as several known IRF5 target genes, including CCL5, CXCL16, and IL23A, suggesting that MDMs from older individuals display an enhanced IRF5-dependent innate immune response to HIV-1 infection." (PMID 40493408, 2025).
Insulin resistance (1 paper, 2020). Increased resistance towards insulin, that is, diminished effectiveness of insulin in reducing blood glucose levels. "Our data showing upregulated adipose tissue expression of IL-23A are relatively new and not much is known how this cytokine influences the other players involved in metaflammation or insulin resistance in obese and/or T2D subjects." (PMID 32188105, 2020).
lung adenocarcinoma (1 paper, 2025). A carcinoma that arises from the lung and is characterized by the presence of malignant glandular epithelial cells. "In lung adenocarcinoma, high expression of CCL20, IL23A, MMP1 and MMP3 was significantly associated with poor patient prognosis, whereas high expression of FOS, HLA-DPA1, HLA-DPB1, HLA-DQA1, HLA-DQB1 and HLA-DRA was significantly associated with improved patient prognosis." (PMID 40016789, 2025).
mesothelioma (1 paper, 2025). A usually malignant and aggressive neoplasm of the mesothelium which is often associated with exposure to asbestos. "Expression of interleukins IL17C, IL23A and IL24 were greater in R- vs NR-mesotheliomas; Benajmini-Hochberg adjusted P values < 0.05." (PMID 40691143, 2025).
non-small cell lung carcinoma (1 paper, 2013). A group of at least three distinct histological types of lung cancer, including non-small cell squamous cell carcinoma, adenocarcinoma, and large cell carcinoma. "We have previously identified IL-23A as pro-proliferative and epigenetically regulated in non-small cell lung cancer (NSCLC)." (PMID 23802098, 2013).
oral cancer (1 paper, 2023). "Elevated expression of proinflammatory genes like s100a9, IL23a, IL1b, and immune checkpoint gene PDCD1/PD1 was reported during oral cancer development in the 4-NQO–induced cancer group in comparison to normal mice, and similar results have also been found in human oral cancer and other cancers." (PMID 37936711, 2023).
osteoporosis (1 paper, 2020). A condition of reduced bone mass, with decreased cortical thickness and a decrease in the number and size of the trabeculae of cancellous bone (but normal chemical composition), resulting in increased fracture incidence. "On the other hand, there was no change in the expression of IL-6, IL-1β or IL-23a, which are cytokines associated with osteoporosis." (PMID 32443893, 2020).
pancreatitis (1 paper, 2022). Inflammation of the pancreas. "The mRNA levels of proinflammatory cytokines, including IL‐23a and Tnf, were significantly increased by AT7519 in cerulean‐induced pancreatitis mice." (PMID 35634959, 2022).
rosacea (1 paper, 2023). A chronic erythematous skin disorder that affects the face. "The expression of proinflammatory innate cytokines, including Th1 polarizing cytokines Il12b and Tnf; Th17/Th22 polarizing cytokines Il1b, Il23a, and Il6; and Il10 were significantly induced as compared with controls showing a similar expression profile as in rosacea." (PMID 36633910, 2023). "Among innate cytokines, we observed a significant increase in TNF, IL1B, IL8, IL12B, IL23A, and IL10 — but not IL36B — in rosacea skin lesions as compared with skin from healthy donors." (PMID 36633910, 2023).
Sepsis (1 paper, 2020). Sepsis is defined as life-threatening organ dysfunction caused by a dysregulated host response to infection. "The lysosomotropic compound NB 06 down-regulates the expression of pro-inflammatory cytokines (e.g., IL-1B, IL-6 and IL-23A in LPS-stimulated macrophages and desipramine protects against sepsis-induced cardiac dysfunction in a murine sepsis model." (PMID 32668803, 2020). "NB 06, like chloroquine, modulates the gene expression of the prominent inflammatory messengers IL-1B, IL-23A, CCL4, CCL20, and IL-6; likewise, it has beneficial effects in (systemic) infections involving bacterial endotoxins, such as LPS, by targeting the TLR4 receptor pathway in sepsis." (PMID 32668803, 2020).
skin tumors (1 paper, 2016). "Ablation of Il23a resulted in marked reduction in DMBA/TPA-induced skin tumors, suggesting a strong tumor-promoting role of IL-23 in the skin." (PMID 31051015, 2016).
tongue cancer (1 paper, 2021). A malignant neoplasm affecting the tongue. "The extract significantly reduces the expression of pro-inflammatory molecules s100a9, interleukin 23 subunit alpha (IL23a), interleukin 1 beta (IL1β) and immune checkpoint gene PDCD1/programmed cell death-1 (PD1) during tongue cancer prevention." (PMID 34765739, 2021).
trachoma (1 paper, 2020). "Given the potential role of the IL-23A/IL-17 axis in trachoma pathogenesis, this could offer a potential explanation as to why females are at greater risk of scarring trachoma than males." (PMID 31964744, 2020). "Nevertheless, IL23A, SPARCL1, and PDGFB may be key mediators driving pathological inflammation and fibrosis in trachoma, and molecules that inhibit their action could hold therapeutic potential in preventing scarring progression." (PMID 31964744, 2020).
ZIKV infection (1 paper, 2019). "ZIKV infection induced increased SC expression of IL-6, interferon (IFN)β1, IFN-λ, IFIT-1, TNFα and IL-23A mRNAs as well as IFN-λ receptors and negative regulators of IFN signaling." (PMID 31289325, 2019).
infection (59 papers, 2009 to 2025). The state of being infected such as from the introduction of a foreign agent such as serum, vaccine, antigenic substance or organism. "In support of these results, we detected increased levels of G-CSF, a hallmark granulopoiesis-inducing cytokine, in the serum of Il23a-/- mice compared to their WT counterparts at 48h post infection." (PMID 31887131, 2019). "We found the expression of il23a (encoding IL23p19) to be transiently upregulated on day 3 post infection (PI), alongside il12b (encoding IL12p40), while il12a (encoding IL12p35) was induced only by day 6 PI." (PMID 25761673, 2015). "Gene expression analysis demonstrated a strong upregulation of IL23A (encodes p19) by infection, whereas IL23R, Epstein–Barr virus-induced gene 3 (EBI3), IL6ST, IL12A, and IL27RA were found to be expressed, but not regulated, or to a lesser extent." (PMID 24069393, 2013). "Conversely, dysregulation of this axis in Il23a−/− and Il22−/− mice leads to high susceptibility to infection with pathogenic bacteria such as Citrobacter rodentium (C. rodentium), a model bacterium for human enteropathogenic and enterohemorrhagic Escherichia coli infection." (PMID 38180443, 2024). "IL-23-dependent IL-17A production has been shown to be critical for defense against C. albicans skin infection in an epicutaneous infection model using Il17af−/− and Il23a−/− mice, and humans with deficiencies in IL-23R signaling show increased susceptibility to CMC." (PMID 28590443, 2017). "IL-23A played a more important role than IL-6 for Th17 differentiation in leprosy which is reminiscent of the report on Mycobacterium bovis infection in a murine model where IL-17 was observed from day 1 of infection, was dependant on IL-23 and associated with granuloma formation." (PMID 23936569, 2013). "The genes encoding for markers of inflammation, namely Tnf, Il1b, Il6, Il23a, and Cxcl10 were induced with infection in Tln1fl/fl mice and significantly decreased in the colon tissues from infected Tln1Δmye mice compared to infected Tln1fl/fl mice." (PMID 38102166, 2023). "BMmacs derived from Tln1fl/fl and Tln1Δmye mice displayed similar levels of induced Tnf, Il1b, Il6, and Il23a transcripts after infection with C. rodentium." (PMID 38102166, 2023). "This confirmed a significant increase in Il1b at 24 h following infection, with minimal induction of Il23a evident, as well as higher levels of monocyte and T cell chemoattractants Ccl4 and Ccl5." (PMID 35845169, 2022). "In contrast, there was a significant reduction or failure in activation of type 2-related chemokines/cytokines (Cxcl12, Ccrl1, Il4, Il23a) and signature markers (Stat3, Stat5b, Stat6, Mrc1, Ahr) during infection." (PMID 34320039, 2021). "IL23A, one of the top 10 highly variable features in the infection group, showed a significant increase in expression only in cluster 0 cells." (PMID 34214113, 2021). "Specifically, drivers of coagulation, including the gene coding for tissue factor F3, as well as pro-inflammatory cytokines IL23A and IL1A were specifically associated with WT infection." (PMID 33529199, 2021). "Further genes pointing towards NF-κB signalling during infection, such as il1b, il23a, nfκbia, tcim and zc3h12a, were also found to be induced by the bacteria in this study in presence or absence of the Erk1/2 inhibitor." (PMID 34863201, 2021). "From the normalized gene expression features, highly variable features were similar in both the control and infection groups, but the infection group showed specific expression of IL23A." (PMID 34214113, 2021). "In the intestine, IL-23A is thought to act synergistically with IL-1β to promote pathogenic ILC and Th17 responses following infection with Helicobacter hepaticus." (PMID 31964744, 2020). "WT and Il23a-/- mice were treated with BrdU during the last 12h before analysis at 48h post infection." (PMID 31887131, 2019).
infection (continued). "In the following, we systemically infected WT and Il23a-/- mice with S. aureus and analyzed kidney myeloid cells for their number and viability at 48h post infection." (PMID 31887131, 2019). "Next, we examined tissue sections at 48h post infection, the time point when the biggest differences in kidney fungal load were observed between Il23a-/- and WT mice." (PMID 31887131, 2019). "We also assessed the rate of granulopoiesis at 24h post infection, when fungal burden was still comparable in WT and Il23a-/- mice by providing BrdU between 12h and 24h post infection." (PMID 31887131, 2019). "The situation was comparable in WT and Il23a-/- mice with similar numbers of neutrophils and Ly6Chi monocytes in both genotypes at 24h post infection." (PMID 31887131, 2019). "Neutrophils in the brain were strongly reduced in Il23a-/- compared to WT mice at 48h post infection as in the kidney." (PMID 31887131, 2019). "To assess myeloid cell viability under conditions when fungal loads were comparable between Il23a-/- and WT mice, we isolated kidney neutrophils at 24h post infection." (PMID 31887131, 2019). "Our gene expression analysis revealed induction of EBI3 by H. pylori co-infected gastric cell lines, and correlation with IL23A expression after P1 strain infection." (PMID 24069393, 2013). "Infection with L. monocytogenes resulted only in weak Il23a induction (∼50 fold less than wildtype L. pneumophila at the same initial multiplicity of infection)." (PMID 21390206, 2011). "In our experiment the IL23A levels were 48 -, 30- and 6-fold elevated after infection with LM, SA and SP, respectively." (PMID 21044323, 2010). "Remarkably, IL23A was positively correlated with EBI3 after infection with P1 strain only (P<.05)." (PMID 24069393, 2013). "As suggested by previous transcriptional profiling experiments, we confirmed that Myd88−/−and Rip2−/−macrophages, which are defective in TLR and Nod1/Nod2 signaling, respectively, strongly upregulated Il23a and Gem following infection with wildtype L. pneumophila." (PMID 21390206, 2011). "However, small alterations in expression of both IL8 and IL23A could still be seen with M2 infection or after application of the filter cap (in case of BCM-300 strain)." (PMID 24069393, 2013). "Similar to F3 and IL23A expression, CXCL8 transcripts were observed at much greater intensity and in a much larger area of tissue in samples from WT vs ΔΔstx infection." (PMID 33529199, 2021). "SCs responded to infection with increased expression of mRNAs for IFNβ, IFNλ, IFIT-1, Mx1, NLRP3, IL-23A, IL-6 and TNFα." (PMID 31289325, 2019). "To validate transcriptional changes in iHOs after infection with S. Typhimurium SL1344, we carried out further microinjections with PBS or SL1344 and measured the mRNAs for IL-8, IL1B, IL23A, TNF, and CXCL2 with quantitative assays." (PMID 25964470, 2015). "The correlation between IL23A and IL6ST was only seen after infection with BCM-300 and P1 strains (P<.05)." (PMID 24069393, 2013). "The upregulation of IL6ST and EBI3 was less pronounced after infection compared to that of IL8 and IL23A." (PMID 24069393, 2013). "Although there appeared to be overall immunosuppressive changes to gene expression in cells infected in ADE compared to conventional infection conditions, select immune signaling molecules were enriched, including top upregulated DEGs CCR7, ISG15, IL23A, and TRAF." (PMID 39902963, 2025). "Along with the high fungal burden, Il23a-/- and Il23rgfp/gfp mice, but not their wildtype counterparts, also displayed signs of pain and severe distress at 48h post infection, indicative of severe systemic disease." (PMID 31887131, 2019). "Mice that after DTx treatment specifically lacked il23a in their CX3CR1+ cell compartment died by day 10–12 after infection." (PMID 25761673, 2015). "Colonic CD11c+ CD64+ CD24+ macrophages, but neither CD103+ CD11b− DC nor CD103− CD11b+ DC responded to the infection with il23a induction." (PMID 25761673, 2015).